LMO3 (LIM domain only 3)
Synonyms: RBTN3; RBTNL2; RHOM3; Rhom-3; DAT1
Tractability: No criterion of Open Targets' tractability assessment is met for any kind of drug.
Gene: Protein-coding gene on chromosome 12 (16,548,148 to 16,613,168, reverse strand). Ensembl gene ENSG00000048540.
Gene Ontology:
Molecular function: protein binding; transcription coactivator activity
Biological process: negative regulation of ERK1 and ERK2 cascade; positive regulation of fat cell differentiation; positive regulation of nuclear receptor-mediated glucocorticoid signaling pathway; positive regulation of peroxisome proliferator activated receptor signaling pathway; positive regulation of transcription by RNA polymerase II
Cellular component: cytoplasm; nucleus
Genetic constraint (gnomAD): Loss-of-function variants: 2 observed, 12.44 expected, observed/expected ratio (o/e) 0.16, 90% interval 0.065 to 0.51. The upper end of that interval is the gene's LOEUF score, 0.51, which puts it in group 2 of 6, group 1 being the genes least tolerant of losing a copy. Missense variants: 57 observed, 144.94 expected, observed/expected ratio (o/e) 0.39, 90% interval 0.32 to 0.49. Synonymous variants: 46 observed, 51.88 expected, observed/expected ratio (o/e) 0.89, 90% interval 0.7 to 1.13.
Homologues: Orthologues: guinea pig LMO3 (100% identical), macaque LMO3 (100% identical), mouse Lmo3 (100% identical), rat Lmo3 (100% identical), dog LMO3 (99% identical), rabbit LMO3 (99% identical), zebrafish lmo3 (99% identical), chimpanzee LMO3 (99% identical), tropical clawed frog lmo3 (98% identical). Paralogues in human: LMO1 (90% identical), LMO2 (44% identical), LMO4 (43% identical), LHX9 (41% identical), LHX2 (41% identical), LHX3 (39% identical), LHX4 (38% identical), LHX8 (38% identical), LHX6 (37% identical), LMX1A (37% identical), LMX1B (37% identical), ZFHX3 (33% identical), and 8 more.
Diseases named in the same sentence as LMO3 in open-access papers:
LMO3 is named in the same sentence as 39 diseases in open-access papers, as found by Europe PMC text mining. Sharing a sentence is not in itself a finding about the gene and the disease. The quoted sentences say what the papers report.
neuroblastoma (14 papers, 2011 to 2025). Neuroblastoma (NB) is the most common solid, extracranial childhood tumor. "Consistent with our findings in EC, elevated LMO3 expression has been associated with poor prognosis in gastric cancer and neuroblastoma, PRKAA2 in endometrial cancer and RAB10 in breast cancer and hepatocellular carcinoma." (PMID 40804485, 2025). "The high levels of LMO3 or Mash1 mRNA expression were significantly associated with poor prognosis in 100 primary neuroblastomas." (PMID 21573214, 2011). "Finally, LMO3 has been implicated in neuroblastoma progression, where the overexpression of LMO3 caused rapid and aggressive tumor growth and was subsequently associated with decreased patient survival." (PMID 37887305, 2023). "Thus, the results obtained from the primary neuroblastomas suggested that both high mRNA expression of LMO3 and Mash1 were strongly associated with poor prognoses of the patients with neuroblastoma but the way of contribution of those seemed to be rather independent." (PMID 21573214, 2011). "Higher levels of LMO3 expression occurred in some of the human neuroblastomas corresponding to cluster 2h based on the adrenergic score, explaining how the adrenergic signature can form in these tumors despite relatively low levels of LMO1 expression." (PMID 37183825, 2023). "Several studies have reported that LMO3 is involved in neuroblastoma and hepatocellular carcinoma (HCC)." (PMID 36199576, 2022). "The oncogenic role of LMO3 in hepatocellular carcinoma, gastric cancer, and neuroblastoma has been reported recently." (PMID 35350839, 2022). "It has been reported that LMO3 is a transcriptional regulator involved in central nervous system development, lung adenocarcinomas and neuroblastomas." (PMID 25829251, 2015). "In neuroblastomas, the increased expression of LMO3 contributes to the tumor development and aggressiveness." (PMID 25829251, 2015). "Although some studies report an oncogenic role for LMO3 in neuroblastoma, our results suggest that, in meningioma, this is only the case in the more benign forms." (PMID 23840654, 2013). "We have also reported that LMO3 (LIM-only protein 3) has an oncogenic potential in collaboration with neuronal transcription factor HEN2 in neuroblastoma." (PMID 21573214, 2011). "Previously, we reported that LMO3 is expressed at significantly high levels in human unfavorable neuroblastomas relative to favorable ones, and has an oncogenic potential in neuroblastoma." (PMID 21573214, 2011). "Interestingly, the human neuroblastomas expressing high levels of LMO3 in cluster 2h are enriched for neuroblastomas with MYCN gene amplification (cluster 2i)." (PMID 37183825, 2023). "Nescient helix-loop-helix 2 binds to LMO3 to downregulate the expression of hes family bHLH transcription factor 1 through transactivation of achaete-scute complex-like 1 and induces malignant transformation of neuroblastoma." (PMID 35350839, 2022). "Moreover, LMO3 has been reported to play important roles in some types of cancer, including neuroblastoma and lung cancer." (PMID 30219064, 2018). "In the disease association analysis (neoplasms, cancer or viral infections, breast neoplasms, neuroblastoma), the LMO3, MYB and BIRC3 oncogenes were also significantly upregulated whereas the WISP2, IGFBP5 and RASSF2 tumour suppressor genes were significantly downregulated in FFs compared to NFs." (PMID 28717200, 2017). "LMO3 has an oncogenic potential in collaboration with HEN2 in neuroblastoma cells." (PMID 21573214, 2011).
neuroblastoma (continued). "This LMO3/HEN2-HES1-Mash1 pathway could be the new future target for developing the anti-neuroblastoma treatment." (PMID 21573214, 2011). "LMO1, LMO2, and LMO3 are functionally redundant T-ALL oncogenes, so, we reasoned that loss of lmo1 expression in zebrafish might stimulate the upregulation of other lmo family members during neuroblastoma pathogenesis." (PMID 37183825, 2023). "To verify whether a significant relationship could be observed between expression of LMO3 and that of Mash1 in primary neuroblastomas, we quantitatively measured the expression levels of LMO3 and Mash1 mRNA in 100 primary tumors by using a quantitative real-time RT-PCR." (PMID 21573214, 2011). "In this regard, it is interesting that aberrantly high LMO3 expression levels appear to be frequent in neuroblastomas with MYCN gene amplification, which may explain the lack of association of the rs2168101 genotype with the risk of developing MYCN-amplified neuroblastomas." (PMID 37183825, 2023). "Interaction of LMO3 with another transcription factor, HEN2, is correlated with poor prognosis of neuroblastoma and tumor growth." (PMID 37887568, 2023). "Our results also revealed that a subset of the GATA/TATA neuroblastomas with lower LMO1 expression can develop in neuroblastomas with the adrenergic CRC, due, in part, to aberrant upregulation of LMO3, a closely related LMO family member." (PMID 37183825, 2023). "This is the case for the neuroblastoma tumors in our UMAP analysis (cluster 2h), which are characterized by lower LMO1 but high LMO3 expression levels." (PMID 37183825, 2023). "Here we found that LMO3 forms a complex with HEN2 and acts as an upstream mediator for transcription of Mash1 in neuroblastoma." (PMID 21573214, 2011). "LMO3 was reported to form a complex with neuronal-specific basic helix-loop-helix (bHLH) transcription factor Helix-Loop-Helix protein 2 (HEN2), which was also expressed at higher levels in unfavorable neuroblastoma than in the favorable type." (PMID 30219064, 2018). "For luciferase reporter assay without siRNA for human LMO3, we used mouse neuroblastoma Neuro2a cells which displayed higher transfection efficiency than human neuroblastoma cells as examined by GFP staining (data not shown)." (PMID 21573214, 2011). "In this study, we found that Mash1 is one of transcriptional targets of LMO3/HEN2 transcriptional complex, and its protein product may play an important role in regulation of neuroblastoma cell growth." (PMID 21573214, 2011). "Thus, our present results suggest that a transcriptional complex of LMO3 and HEN2 may contribute to the genesis and malignant phenotype of neuroblastoma by inhibiting HES1 which suppresses the transactivation of Mash1." (PMID 21573214, 2011). "Thus, it is likely that the balance between intracellular amounts of HES1 and LMO3/HEN2 might determine expression levels of Mash1, and thereby regulating neuroblastoma cell growth." (PMID 21573214, 2011). "In this study, we examined whether there could exist functional relationship between LMO3/HEN2 and Mash1 in neuroblastoma, and found that LMO3/HEN2 attenuates HES1 function and enhances transactivation of Mash1, leading to aggressive phenotype of neuroblastoma." (PMID 21573214, 2011).
glioma (9 papers, 2015 to 2025). A benign or malignant brain and spinal cord tumor that arises from glial cells (astrocytes, oligodendrocytes, ependymal cells). "MiR-101 inhibits the expression of EZH2 and DNMT3A, which leads to increased levels of H3K4me3 and H4K20me3 in the core promoter region of LIM domain only 3 (LMO3), thereby inhibiting the expression of LMO3 and metastasis of glioma cells." (PMID 36497343, 2022). "The LIM-only protein 3 (LMO3) was first identified in glioma and is considered as a DNA methylation gene." (PMID 35236381, 2022). "By inhibiting EZH2, miRNA-101 diminishes promoter occupation of LMO3 by H3K27me3 and prevents its methylation, resulting in glioma suppression." (PMID 35236381, 2022). "LMO3 is often overexpressed in gliomas and its expression correlates positively with poor prognosis." (PMID 31963147, 2020). "miR-101 epigenetically suppresses the expression of LIM domain only 3 (LMO3) by inhibiting the binding of Upstream stimulatory factor 1 (USF) and Myeloid Zinc Finger 1 (MZF1) to the LMO3 promoter and induces cell apoptosis in U251 glioma cells." (PMID 30583549, 2018). "In this study, we found that LIM-only protein 3 (LMO3) is hypomethylated and overexpressed in glioma cells and tissues." (PMID 25829251, 2015). "In this study, we confirmed the function of miR-101 in glioma cell apoptosis and demonstrated that miR-101 suppresses the expression of LMO3 through histone modification-induced hypomethylation." (PMID 25829251, 2015). "We previously demonstrated that the LMO3 gene, located at 12p12.3, is hypomethylated in glioma tissues." (PMID 25829251, 2015). "The overexpression of LMO3 was correlated with a poor prognosis in glioma patients, and LMO3 was indirectly inhibited by the tumor suppressor miR-101, which is a potential prognosis marker of gliomas." (PMID 25829251, 2015). "Having established the hypomethylation role for LMO3 in gliomas, we next aimed to clarify the regulatory mechanism of LMO3 expression." (PMID 25829251, 2015). "To further confirm the hypomethylation of LMO3 in gliomas, we designed and validated the BSP and MSP methods." (PMID 25829251, 2015). "The expression of LMO3 in normal brain tissues was lower compared to the glioma cell lines, and increased expression of the LMO3 protein was found in the glioma cell lines and in 37 of the 50 glioma tissues." (PMID 25829251, 2015). "In this study, we found that the occupancy of H3K4me2 and H3K27me3 was decreased by miR-101, whereas the occupancy of H3K9me3 and H4K20me3 was increased at the LMO3 core promoter in glioma cells." (PMID 25829251, 2015). "Furthermore, ectopic expression of miR-101 decreases H3K27me3 occupancy on an oncogenic transcription cofactor protein LIM domain-only protein 3 (LMO3) in gliomas." (PMID 37345170, 2023). "In our study, miR-101 was shown to induce glioma cell apoptosis by indirectly inhibiting LMO3." (PMID 25829251, 2015). "Aside from hypomethylation, the mechanisms of LMO3 dysregulation in gliomas is unclear." (PMID 25829251, 2015). "LMO3 can therefore be considered to be a new indirect target of miR-101 in gliomas." (PMID 25829251, 2015). "Furthermore, miR-101 could reverse the hypomethylation of the LMO3 promoter in glioma cells." (PMID 27911279, 2017). "The occupancy of the methylation-related histones (H3K4me2, H3K27me3, H3K9me3 and H4K20me3) on the LMO3 promoter was detected after the inhibition of EZH2, EED and DNMT3A in glioma cells." (PMID 25829251, 2015). "LIM-only protein 3 (LMO3), a member of the LIM-only protein group, is a new DNA methylation gene that was identified in gliomas via the MeDIP-Chip in our previous study." (PMID 25829251, 2015).
glioma (continued). "LIM-only protein 3 (LMO3), a member of the LIM-only protein group, is a new DNA methylation gene that was identified in gliomas via the MeDIP-Chip." (PMID 25829251, 2015). "In glioma cell lines, MZF1 binds directly to the LIM-only protein 3 (LMO3) promoter and induces the expression of LMO3, which is a transcriptional co-activator that can act as an oncogene in glioma, one of the most aggressive and most common tumors of the central nervous system." (PMID 31963147, 2020). "However, we identified that miR-101 inhibits the expression of LMO3 not by binding to its 3′-UTR but in an indirect way in glioma cells." (PMID 25829251, 2015).
hepatocellular carcinoma (6 papers, 2018 to 2025). A malignant tumor that arises from hepatocytes. "In this research, we aimed to investigate the biological functions of LIM domain only 3 (LMO3) in hepatocellular carcinoma (HCC) and uncover the underlying molecular mechanism in it." (PMID 30219064, 2018). "LATS1, the key regulator of the Hippo pathway, was found to be a binding partner of LMO3 during tumorigenesis of hepatocellular carcinoma." (PMID 35350839, 2022). "In hepatocellular carcinoma, LMO3 directly interacts with LATS1 and suppressing Hippo signaling to promote invasion and metastasis." (PMID 32195177, 2020). "It was revealed that LIM domain only 3 (LMO3) could inhibit anoikis to promote hepatocellular carcinoma metastasis by suppressing the Hippo pathway." (PMID 36347846, 2022). "Therefore, LMO3 was considered to be an oncogene in the progression of gastric cancer, glioma, and hepatocellular carcinoma." (PMID 35350839, 2022). "Research has shown that LMO3 directly interacts with large tumor suppressor kinase (LATS) 1 to inhibit the phosphorylation of LATS1 and promote Rho GTPases activities, thus suppressing Hippo signal to promote the invasion and metastasis of hepatocellular carcinoma." (PMID 35350839, 2022).
lung adenocarcinoma (5 papers, 2013 to 2022). A carcinoma that arises from the lung and is characterized by the presence of malignant glandular epithelial cells. "Regarding overall survival (OS), LMO3 was related to the prognosis of kidney renal clear cell carcinoma, liver hepatocellular carcinoma, lung adenocarcinoma, and uterine corpus endometrial carcinoma." (PMID 36199576, 2022). "The ChIP-seq data indicate that NKX2-1 binds to three distinct regions (ATAC inaccessible) at the second intron of LMO3, a product of which is involved in the survival of lung adenocarcinoma cells." (PMID 33980985, 2021). "Furthermore, NKX2-1 enhances together with FOXA1 survival in lung adenocarcinoma by transcriptional activation of LMO3." (PMID 23637834, 2013). "In lung adenocarcinomas bearing a NK2 homeobox 1 (NKX2-1) amplification, the oncogenic capacity of LMO3 as a transcription regulator downstream of NKX2-1 has been demonstrated." (PMID 25923053, 2015).
Obesity (5 papers, 2013 to 2024). Accumulation of substantial excess body fat. "SLC15A5 is responsible for protein transport through membranes and LMO3 was shown to contribute to reprogramming of adipose tissue depots during obesity, thereby modulating nutrient homeostasis." (PMID 36980854, 2023). "LMO3 is expressed in adipocytes and is thought to regulate genes that promote adipose tissue functionality in obesity." (PMID 38201877, 2023). "Our data expand greatly upon our previous studies of LMO3 function during adipogenesis to illuminate the role of this protein in mature fat during obesity." (PMID 34018016, 2021). "The aim of this study was to determine the potential involvement of LMO3-dependent pathways in the modulation of key functions of mature adipocytes during obesity." (PMID 34018016, 2021). "LMO3 expression in visceral adipose tissue regulates multiple genes that preserve adipose tissue functionality during obesity, such as glucose metabolism, insulin sensitivity, mitochondrial function, and adiponectin secretion." (PMID 34018016, 2021). "Here, we developed an AAV-based, visceral adipose tissue specific “Lmo3 knock-in” mouse model to investigate the potential involvement of LMO3 in the modulation of key (visceral) adipocyte functions during obesity." (PMID 34018016, 2021). "Together, our data show that LMO3 expression in eWAT significantly improves glucose clearance in diet-induced obesity and that these effects may be due to increased glucose uptake and mitochondrial functionality by mature adipocytes." (PMID 34018016, 2021). "To test whether LMO3 expression affects the function of mature adipocytes in eWAT during obesity, we injected rAAV-YFP or rAAV-Lmo3 bilaterally, followed by 10 weeks on chow or HFD." (PMID 34018016, 2021). "LMO3 expression is undetectable throughout differentiation of murine primary preadipocytes and remains undetectable in WAT of a genetic obesity mouse model (db/db) and HFD-challenged mice." (PMID 34018016, 2021).
gastric cancer (4 papers, 2018 to 2025). A primary or metastatic malignant neoplasm involving the stomach. "LMO3 has been proved to promote cell invasion or proliferation through Akt-mTOR/GSK3β signaling in gastric cancer." (PMID 30219064, 2018). "LMO3 could promote gastric cancer cell invasion and proliferation through Akt-mTOR and Akt-GSK3β signaling pathways." (PMID 32195177, 2020).
Anxiety (2 papers, 2023 to 2025). Intense feelings of nervousness, tension, or panic often arise in response to interpersonal stresses. "Loss of LMO3 has also been shown to induce the adoption of depressive and anxiety-like behavioral phenotypes in LMO3 knockout mouse models and to alter animal response to ethanol administration." (PMID 37887305, 2023). "To understand whether activating ASIC4-expressing cells could modulate fear and anxiety responses, we applied chemo-optogenetic approaches by using Asic4CreERT2::LMO3 mice." (PMID 40264173, 2025).